CXCR4 (C-X-C motif chemokine receptor 4)
Diseases named in the same sentence as CXCR4 in open-access papers (continued):
Sharing a sentence is not in itself a finding about the gene and the disease.
tumor (continued). "In addition, ampelopsin restricted the lymph node and lung metastasis in orthotopic PC-3 tumor model in mice, associated with the suppression of CXCR4 levels." (PMID 39465008, 2024). "It is possible that signaling through CXCR4 could be counterproductive when using KineTACs to target cancer drivers because CXCR4 overexpression and agonism are linked to tumor metastasis." (PMID 36138170, 2023). "Furthermore, the correlation between BRAF, KRAS, NRAS mutations, and FAP and CXCR4 in both the primary tumor and the first metastasis were examined." (PMID 37892020, 2023). "Tumor microenvironment genes linked to ocular angiogenesis include Spp1, Csf1, and Cxcr4." (PMID 37858232, 2023). "However, some studies have reported that KRAS G12V mutations upregulate the expression of CXCR4 and proinflammatory genes in the tumor microenvironment, leading to immune suppression and promoting tumor growth and metastases." (PMID 37415118, 2023). "The CXCR4 expression was associated with tumor differentiation (P-value = 0.05)." (PMID 37697316, 2023). "Although both invasion types have been associated with tumour growth and metastatic potential, the collective sheet migration relies upon heterogeneity in the cells, where “leader” cells display specific receptors, including CXCR4 and CXCR7." (PMID 36835368, 2023). "Remarkably, several of these target genes were down-regulated following miR-Combo treatment, and have been shown to be involved in GBM progression (RAP2A), angiogenesis (SPON2), migration (CXCR4), and are associated with an increase in tumor grade (IGF2BP3, SERPINH1)." (PMID 37749143, 2023). "One blocks AML dissemination in different mouse models; however, it is associated with on-target and off-tumor toxicity in BM, showing a reduction in CXCR4+ granulocyte-monocyte progenitors and erythroblasts and a decrease in neutrophils and monocytes in the blood." (PMID 36986589, 2023). "In malignancies, increased CXCR4 expression is associated with tumor growth, angiogenesis, and metastasis and may lead to resistance towards therapy." (PMID 36672341, 2023). "Further, it was also reported that curcumin strongly hindered tumor EMT through downregulating Nkd2-Wnt-CXCR4 signaling, then mediation of EMT-associated markers E-cadherin and vimentin expressions, resulting in a reduction of invasive and metastatic abilities in SW620 CRC cells." (PMID 35308223, 2022). "CXCL12 and its receptor CXCR4 have been implicated in tumor growth and metastasis in a variety of cancers, and CXCL12 expression has been observed in the tumor microenvironment and cancer cell cytoplasm and plasma membranes, but not focused on the plasma membrane 7-10." (PMID 34976180, 2022). "Furthermore, CXCR4 knockdown strongly reduces in vivo tumor growth associated with the reduction of tumor capillaries and intra-tumoral blood flow without affecting VEGF expression." (PMID 35406582, 2022). "Tip cells highly overexpress CXCR4 compared to other EC phenotypes and are characterized by induced pro-angiogenic pathways associated with vascular development, vasculogenesis, EC development and tumor angiogenesis." (PMID 35717322, 2022). "Some studies have shown that high expression of SDF-1 in cancer cells attracts CXCR4-positive cells, such as cancer-associated fibroblasts (CAFs) or tumor infiltrating lymphocytes (TILs), to the tumor sites and converts the tumor microenvironment (TME) to immune tolerance." (PMID 36341391, 2022). "However, focusing on the first two years of follow-up the high ratio of pCXCR4/CXCR4 tumor infiltrating immune cells showed a trend that was associated with a better RFS (p = 0.025)." (PMID 35397601, 2022).
tumor (continued). "This induces tumor-associated macrophage (TAM) migration through the CXCL12/CXCR4 pathway." (PMID 36577755, 2022). "In addition, CXCR2 and CXCR4, which are associated with pro-tumor in ICIs, were shown to be lower in PTPRD/PTPRT mutant cancers compared with WT (both P < 0.01)." (PMID 36248841, 2022). "CXCL12 and CXCR4 are expressed at significantly increased levels in gastrointestinal cancers, and this overexpression is associated with the activation of downstream pathways and survival, proliferation, angiogenesis, and migration of tumor cells." (PMID 35877436, 2022). "Besides, tumor-associated macrophage accelerates the survival of CRPC cells upon docetaxel chemotherapy via the CSF1/CSF1R-CXCL12/CXCR4 axis." (PMID 36686485, 2022). "Here we find further evidence of this hypothesis indicating that higher expression of the motility marker CXCR4 on CAMLs appears to relate to an increase of all tumor associated cells in circulation, including CTCs." (PMID 35259193, 2022). "Examples of cytokine-receptor pairs implicated in MSC tumour tropism are SDF-1 & C-X-C motif chemokine receptor-4 (CXCR4), VEGF & VEGFR, MCP-1 & C-C motif chemokine receptor (CCR2), epidermal growth factor (EGF) & EGFR, and hepatocyte growth factor (HGF) & c-Met." (PMID 35103937, 2022). "Although post‐irradiation CXCR4‐mediated angiogenesis is associated with radioresistance and recurrence after the radiotherapy through rescuing the damaged tumor vasculature caused by radiation, upregulated CXCR4 was associated with better response to radiotherapy in this study." (PMID 35505641, 2022). "In addition, the enhanced survival of docetaxel-treated PCa cells was mainly mediated by CXCR4 activation from the increased secretion of CXCL12 from CSF-1-activated tumor-associated macrophages." (PMID 35406450, 2022). "However, focusing only on the first two years of follow-up the high ratio of pCXCR4/CXCR4 tumor infiltrating immune cells was significantly associated with a better RFS (p = 0.025)." (PMID 35397601, 2022). "In addition, the high expression of CXCR4 is often associated with tumor metastasis and poor prognosis." (PMID 35064116, 2022). "CRC cells that express high CXCR4 levels have been shown to be more invasive and are associated with worse long term survival, and expression has been reported to be higher in colorectal liver metastases than the primary tumour." (PMID 36140541, 2022). "CXCR4 has been implicated in the onset of a great number of tumors, due to the reason that this receptor is considered to be crucial in immune cells chemotaxis, tumor cell proliferation, invasion, metastasis, and angiogenesis." (PMID 35978426, 2022). "The role of miR-494-3p as a tumor suppressor is most likely linked to the CXCR4 (C-X-C chemokine receptor 4) regulator, although the exact mechanism is unknown." (PMID 36003502, 2022). "Additional molecular biomarkers identified throughout the inflammatory microenvironment of VS that may contribute toward tumor-induced hearing loss include tumor necrosis factor alpha (TNFα), IL-6, CXCR4, and nuclear factor kappa-B (NFκB) activation." (PMID 35372070, 2022). "However, DPP4 displays an antioncogenic function in those tumors linked to the CXCL12/CXCR4 axis, which is known to support neovascularization, tumor growth and metastasis during cancer development." (PMID 33525607, 2021). "Finally, the SW839 cells with CXCR4 deficiency and overexpression were used to establish xenograft tumor-bearing mice models, and the tumor weight and volume were, respectively, monitored." (PMID 34180759, 2021). "We hypothesized differences in spleen CXCR4 expression measured by [68Ga]Pentixafor-PET could potentially be associated with tumor metabolism/activity." (PMID 34417915, 2021). "CXCR4 overexpression accelerated tumor growth of HCC, which was abrogated by c‐Met deficiency." (PMID 34555268, 2021).
tumor (continued). "CXCL12, a ligand for CXCR4, encodes a protein that acts as a G protein-coupled receptor and is involved in cell processes including immune surveillance, inflammatory responses, and tumor metastasis." (PMID 32235004, 2020). "In line with this, it has been recently demonstrated that deficiency in either of the two TNFRs caused a diminished accumulation of MDSCs in the tumor bed and the cause underlying this effect was the downregulation of CXCR4 expression on the surface of MDCSs in a breast cancer model." (PMID 32391269, 2020). "A third reported PDAC cancer stem cell marker, CXCR4, has also been associated with drug resistance, but again there was no consistent pattern of increased or decreased expression of this marker protein in gemR tumor models." (PMID 33073205, 2020). "As a consequence of CXCL12 release, tumor-associated CXCR4-expressing ECs proliferate." (PMID 32983169, 2020). "Moreover, for the first time, normal stromal cells and tumor-associated stromal cells were investigated for CXCR4 mRNA and protein expression." (PMID 32110952, 2020). "Notably, circRNAs targeting CXCR4 in tumor tissue represent a new insight in TAM-associated tumor invasion." (PMID 32943996, 2020). "Therefore, through a bioinformatics analysis of TCGA, it is possible to explore the tumor-associated genomic landscape of CXCR4." (PMID 32260318, 2020). "Furthermore, in the mouse Lewis lung carcinoma model, inhibition of Cxcr4 greatly reduced tumour-associated inflammation and tumour growth." (PMID 32325966, 2020). "In addition, high CXCR4 expression was associated with more advanced tumor stage, worse prognosis and higher stromal score, immune score, and cytolytic activity (P < 0.05)." (PMID 32306562, 2020). "High expression of CXCR4 by tumor cells has been associated with treatment resistance." (PMID 31802362, 2020). "Furthermore, for the first time, we demonstrate that tumor-associated stromal cells express increased CXCR4 mRNA." (PMID 32110952, 2020). "It remains unknown whether MDMX similarly can regulate VEGF or E-cadherin, but we observed that MDMX expression positively correlates with increased tumor-associated CXCR4 expression." (PMID 31489110, 2019). "Interestingly, studies have reported that CD9 and CXCL12 are associated in a CD9/CXCL12/CXCR4 signaling pathway, and activation of this pathway is linked to increased tumor invasion, metastasis, and chemoresistance." (PMID 31191817, 2019). "However, the CXCL12-CXCR4 axis has been linked to tumor proliferation, metastasis, and stroma-induced protection from anti-cancer treatment; and CXCR4 expression has been associated with poor prognosis." (PMID 30774774, 2019). "Blocking of CXCL12 or CXCR4 could prevent the influx of tumor associated macrophages and myeloid suppressor cells which mediate re-vascularization and immunosuppression respectively." (PMID 30813533, 2019). "Importantly, high CXCR4 expression is associated with the presence of tumor ulceration and thicker lesions, as well as shorter disease-free survival, time to metastasis and overall survival." (PMID 30420855, 2018). "The chemo-resistant variants' augmented expression of CXCR4 was associated with an increased susceptibility to viral infection and doxorubicin-mediated killing compared to parental counterparts in vitro and in tumor-challenged mice." (PMID 30622535, 2018). "Indeed, DAPT-mediated Notch inhibition causes a decrease in tumor cells growth and migration through the downregulation of CXCR4 and CXCL12 expression." (PMID 30154786, 2018). "Notably, auto-/paracrine SDF-1/CXCR4 signaling is required for maintenance of stemness and self-renewal capacity since SDF-1/CXCR4 targeting leads to loss of stem cell markers and differentiation of stem(-like) cells into “differentiated” tumor bulk." (PMID 30622535, 2018). "Tumor expression of CXCR4 is associated with poorer survival in PC patients." (PMID 29930538, 2018).
tumor (continued). "As the C-terminal portion plays a critical role in the regulation of signal transduction and CXCR4 expression, further analysis is under investigation to determine whether these mutations are tumor specific and clinically relevant to WM pathogenesis." (PMID 30026568, 2018). "Moreover, high CXCR4 tumor expression associates with metastatic dissemination and confers poor patient prognosis, a finding similar to other cancers." (PMID 30190334, 2018). "CXCR4 over-expression has been associated with tumor cell proliferation, invasion, and metastasis." (PMID 30564115, 2018). "Overall, this platform allowed the dissection of IFN-DC-cancer cell interactions within 3D tumor spaces, with the discovery of major underlying factors such as CXCR4 involvement and underscored its potential as an innovative tool to assess the efficacy of immunotherapeutic approaches." (PMID 28439087, 2017). "In addition to its physiological role, CXCL12/CXCR4 signaling has been implicated in driving tumor cell proliferation, survival and migration in various solid tumors." (PMID 28055968, 2017). "Furthermore, it has been demonstrated that an increased CXCR4 expression is associated with advanced tumor stage and poor patient outcome also in neuroendocrine tumors." (PMID 29163802, 2017). "Our findings suggest that the co-administration of photon irradiation and the CXCR4-antagonist AMD3100 or the use of carbon ions instead of photons may be possible solutions to reduce the risk of locoregional tumor recurrence after radiotherapy for MPM." (PMID 28978091, 2017). "Also in CCC patients, CXCR4 positivity of tumor vessels was associated with an elevated Ki-67 index of the tumor (p = 0.037)." (PMID 29282035, 2017). "CXCR4 expression on tumor vessels was associated with poor patient outcomes." (PMID 29282035, 2017). "Additionally, CXCR4 over-expression has been shown in more than 20 different tumor entities and increased CXCR4 expression has been associated with rapid tumor progression, high invasiveness, early metastasis and poor patient outcome." (PMID 29163802, 2017). "Despite its inhibitory effect on hepatic fibrogenesis, sorafenib may activate the SDF-1/CXCR4 pathway and increase tumor-associated fibrosis in HCC." (PMID 28423574, 2017). "CXCL12 and CXCR4 are always expressed at significantly increased levels in gastrointestinal cancers, which is associated with the activation of downstream pathways and survival, proliferation, angiogenesis, and migration of tumor cells." (PMID 28544785, 2017). "The CXCL12/CXCR4 pair is indeed involved in the increased survival and/or proliferation of cancer cells from various types including virus-related cancers, as well as in the promotion of tumor metastasis and angiogenesis linked to tumor progression." (PMID 27918748, 2016). "Since RUNX2 is a transcription factor, we used bioinformatics analysis to identify genes potentially targeted by RUNX2 W. Among genes linked to tumor cell invasion and metastasis, six candidates were identified with the highest score for the gene encoding a chemokine receptor CXCR4." (PMID 27007162, 2016). "Furthermore, CXCL12 production is triggered in hypoxic environments in tumor cells and is implicated in the promotion of tumor growth in mouse prostate tumors following overexpression of its receptor CXCR4." (PMID 27834814, 2016). "Interestingly, recent studies have indicated the pivotal role of CXCL12/CXCR4 expression in tumor metastasis, showing that it is actively implicated in angiogenesis." (PMID 27668882, 2016). "In addition, the frequency of increased concentrations was the highest for CXCL12 with CXCR4 levels in combination (94%) and improved the diagnostic sensitivity of combined measurement of classical tumor markers—CEA with SCC-Ag (33%)." (PMID 27041792, 2016).
tumor (continued). "The underlying mechanisms whereby CXCR4 exerts its prognostic impact may include tumor growth promotion, apoptosis inhibition, decreased T cell infiltration and immune responses, and tumor cell dissemination to distant organs/tissues." (PMID 25704881, 2015). "CXCR4 is a key regulator of the EMT process through which it could activate signals associated with tumor progression." (PMID 26318034, 2015). "High cell surface expression of CXCR4 has been associated with metastatic activity of tumor cells." (PMID 25775124, 2015). "The goal of the present study was to determine whether AFP can regulate the expression of CXCR4, a chemokine receptor that has been closely associated with tumor cell invasion and metastasis and the underlying mechanisms." (PMID 25815363, 2015). "Furthermore, many studies have shown that increased CXCR4 expression is associated with early metastasis, tumor recurrence, and poor patient outcome." (PMID 26259237, 2015). "Additionally, the expression of CXCR4 by cancer cells seems to be associated with malignancy potential and tumor recurrence." (PMID 25671300, 2015). "The difference of the expression level of CXCR4 in the metastatic cancer cells in our study and in previous reports may be caused by the different tumor amount and incubation period." (PMID 26083776, 2015). "Additionally, CXCR4 expression in tumor cells was associated with metastasis of many human malignancies favoring their migration and homing toward CXCL12 expressing organs (lung, liver, brain, lymph nodes, bone marrow; Teicher and Fricker, 2010)." (PMID 24904289, 2014). "Furthermore, the treatment with 100 μM of OME significantly decreased the expression of the chemokine receptor CXCR4, closely associated with tumor migratory ability (p = 0.0209)." (PMID 25329465, 2014). "Hypoxia enhances CXCL12 secretion in cancer-associated fibroblasts which in turn feeds tumor development either by direct stimulation of tumor cells expressing CXCR4 (paracrine effect) or recruiting endothelial cells for angiogenesis (endocrine effect; Burger and Kipps, 2006)." (PMID 24904289, 2014). "In AML blocking of SDF/CXCR4 by AMD3100 is associated with a rise in circulating tumour cells." (PMID 25294819, 2014). "Additionally, the expression of CXCR4 is modulated by the stroma, which is also associated with progression of the tumor." (PMID 24416254, 2014). "The results indicated that blockade of CXCR4 expression significantly inhibited tumor cell migration and adhesion to the matrix (P<0.05), indicating that the upregulation of CXCR4 causes epithelial cell instability and promotes tumor cell migration and infiltration." (PMID 25202367, 2014). "Up-regulation of CXCR4 is associated with increased metastasis and poor prognosis in various forms of cancer, in part due to effects on cellular phenotype, and is associated with chemotherapeutic resistance in numerous tumor models." (PMID 23442791, 2013). "Tumors derived from the MCF10DCIS.com xenograft showed increased expression of SDF-1 in stromal cells, which is known to be highly induced by tumor-associated fibroblasts, with increased expression of CXCR4, in epithelial cancer cells during the DCIS to IDC transition." (PMID 23401782, 2013). "Furthermore, in Ewing’s sarcoma, up-regulated expression of CXCR4 in tumor tissue specimens was found associated with a high propensity for metastasis and the expression of CXCR7 was an indicator for poor patient survival." (PMID 24040160, 2013). "To address this hypothesis, we analyzed the expression levels of CSCs markers ALDH and SOX2 and tumor stroma-associated markers CXCR4, SDF-1, VEGFR1, CD11b and α-sma in primary tumor and metastatic nodules." (PMID 24278179, 2013). "However, the association between the expression levels of MIF and CXCR4 in diverse cell populations of the tumor microenvironment and the survival of cancer patients remains ambiguous." (PMID 23497377, 2013).